EIF2S1 (eukaryotic translation initiation factor 2 subunit alpha)
Diseases named in the same sentence as EIF2S1 in open-access papers:
EIF2S1 is named in the same sentence as 57 diseases in open-access papers, as found by Europe PMC text mining. Sharing a sentence is not in itself a finding about the gene and the disease. The quoted sentences say what the papers report.
breast carcinoma (5 papers, 2013 to 2024). "Of note, EIF2S1 plays an important role in protein translation initiation, and its expression is significantly increased after chemotherapy in breast cancer patients." (PMID 34900672, 2021). "Furthermore, Fluorescence‐activated cell sorting (FACS) analysis of breast cancer cells treated with paclitaxel also revealed that knockdown of EIF2AKs sensitized cells to paclitaxel‐induced apoptosis, and these effects mainly through EIF2S1 phosphorylation." (PMID 31211507, 2019). "This is consistent with the previous observation that suppressing EIF2S1 activity leads to reduced GSH levels and impaired ROS scavenging in breast cancer." (PMID 39465005, 2024). "Here, we showed that paclitaxel, the major chemotherapy drug for breast cancer, induced ISR and phosphorylated ser51 residue of EIF2S1 by EIF2AK3 and EIF2AK4." (PMID 31211507, 2019).
hepatocellular carcinoma (4 papers, 2020 to 2025). A malignant tumor that arises from hepatocytes. "For example, EIF2S1 knockdown suppressed cell invasion/migration in liver cancer and correlated with poor prognosis in hepatocellular carcinoma." (PMID 40365898, 2025).
liver cancer (4 papers, 2021 to 2025). An epithelial or non-epithelial malignant neoplasm that arises from the liver. "The degree of aggressiveness and prognosis of liver cancer were closely correlated with elevated EIF2S1 expression levels." (PMID 39593796, 2024). "EIF2S1 expression level in liver cancer is increased and is closely related to the degree of malignancy and prognosis of the disease." (PMID 34900672, 2021). "EIF2S1 can affect the invasion and metastasis ability of liver cancer." (PMID 34900672, 2021). "Overall, EIF2S1 plays an important role in the invasion and metastasis of liver cancer." (PMID 34900672, 2021). "Overall, EIF2S1 could affect liver cancer’s invasion and metastasis ability." (PMID 39593796, 2024). "Therefore, the post-transcriptional regulation of EIF2S1 and HDGF plays a key role in the progression of liver cancer patients." (PMID 34094926, 2021).
lung carcinoma (4 papers, 2007 to 2022). "EIF2S1 interacts with TOR signaling modulator-like (TIPRL) proteins to induce autophagy and enhance lung cancer malignancy." (PMID 34900672, 2021).
head and neck squamous cell carcinoma (2 papers, 2023). A squamous cell carcinoma that arises from any of the following anatomic sites: lip and oral cavity, nasal cavity, paranasal sinuses, pharynx, larynx, and salivary glands. "In this study, the EIF2S1 gene and its encoded protein were overexpressed in head and neck squamous cell carcinoma (HNSCC) and associated with shorter overall and disease-free survival." (PMID 38001610, 2023).
leukemia (2 papers, 2013 to 2016). A malignant (clonal) hematologic disorder, involving hematopoietic stem cells and characterized by the presence of primitive or atypical myeloid or lymphoid cells in the bone marrow and the blood. "In leukemia cells, the phosphorylation of EIF2S1 also inhibits the activities of nicotinamide phosphoribosyltransferase (NAMPT), a factor known to regulate cancer cell metabolism." (PMID 28018022, 2016). "EIF2S1, a key regulator in apoptosis signaling pathway, may play a critical role in 6-shogaol-mediated lethality in leukemia cells." (PMID 24215632, 2013).
melanoma (2 papers, 2023 to 2025). A malignant, usually aggressive tumor composed of atypical, neoplastic melanocytes. "We found that SA strongly induced phosphorylation of eukaryotic initiation factor 2α (EIF2S1) in all tested melanoma cell lines, a hallmark of SG formation via the HRI kinase pathway." (PMID 41148289, 2025). "Key to SG formation is the phosphorylation of eukaryotic initiation factor 2α (EIF2S1), a process that was robustly induced by SA in all melanoma cell lines tested, implicating activation of the HRI kinase pathway." (PMID 41148289, 2025). "Activity of the protein kinase PERK was indirectly quantified using phosphorylated eIF2α (Eukaryotic translation initiation factor 2 subunit alpha) and showed a strong increase after the CAP treatment of the melanoma cell line Mel Juso." (PMID 36831408, 2023).
acute lymphoblastic leukemia (1 paper, 2022). Leukemia with an acute onset, characterized by the presence of lymphoblasts in the bone marrow and the peripheral blood. "A recent study demonstrated that WFA induces phosphorylation of the translation initiating factor eIF2S1 and subsequent inhibition of protein translation in T acute lymphoblastic leukemia cells." (PMID 35368048, 2022).
alcohol addiction (1 paper, 2017). "Moreover, potassium channel genes, such as Kcnma1, which have been implicated in METH and alcohol addiction and genes, such as Eif2s1 and Ehd4, are implicated in drug abuse or reward circuits (Supplemental References)." (PMID 28751711, 2017).
atherosclerosis (1 paper, 2024). A disease characterized by the build-up of fatty material and calcium deposition in the arterial wall resulting in partial or complete occlusion of the arterial lumen. "Then, KEGG pathway analysis revealed that these genes were enriched in “lipid and atherosclerosis” (Ncf1, Eif2s1, Tank, Vav1, Nfe2l2), “B-cell receptor signaling pathway” (Blnk, Dapp1, Vav1), and “Fc gamma R-mediated phagocytosis” (Prkcg, Ncf1, Vav1)." (PMID 38952478, 2024).
cataract (1 paper, 2024). Partial or complete opacity of the crystalline lens of one or both eyes that decreases visual acuity and eventually results in blindness. "Based on this, it was speculated that PDGFRB and CDKN1A were promoting genes, and PTEN, CANX, COL4A2, EIF2S1, and NPM1 were suppressing genes in cataract pathogenesis." (PMID 38662949, 2024).
erythroleukemia (1 paper, 2023). Acute erythroid leukemia characterised by the presence of at least 50% erythroid precursors and at least 20% myeloblasts in the bone marrow. "The phosphorylation of eIF2S1 limits translation and cell proliferation, and the proliferation defects seen in both Abcb10-null K562 and MEL erythroleukemia cell lines could be recovered by increasing arginine levels in growth media." (PMID 37269954, 2023).
Hepatitis C (1 paper, 2023). "In addition, the six upregulated DETGs are involved in Hepatitis C, including CDKN1A, TRAF3, CXCL10, CASP3, EIF2S1, and IFIT1." (PMID 37107704, 2023).
Hypoglycemia (1 paper, 2021). A decreased concentration of glucose in the blood. "Eif2s1(tm1RjK) mice, in which Ser51 of eukaryotic initiation factor 2 subunit alpha (eIF2α, the homolog of EIF2S1) is mutated, do not survive after birth due to hypoglycemia associated with defective gluconeogenesis caused by a homozygous mutation." (PMID 34202873, 2021).
lung adenocarcinoma (1 paper, 2023). A carcinoma that arises from the lung and is characterized by the presence of malignant glandular epithelial cells. "Our study identified a novel m6A-related ferroptosis-associated six-gene signature (comprising SLC2A1, HERPUD1, EIF2S1, ACSL3, NCOA4, and CISD1) for predicting lung adenocarcinoma prognosis, yielding a useful prognostic biomarker and potential therapeutic target." (PMID 37072786, 2023).
measles (1 paper, 2023). A highly contagious viral infection caused by the measles virus. "Regarding the measles pathway, the M group showed significant upregulation of three genes (HSPA1, NFKBIA, and EIF2S1), while the L group displayed upregulation of two genes (HSPA1 and NFKBIA)." (PMID 37759582, 2023).
myocardial ischemia (1 paper, 2024). A disorder of cardiac function caused by insufficient blood flow to the muscle tissue of the heart. "In the context of myocardial ischemia, EIF2S1 undergoes phosphorylation and activation by PERK (protein kinase R-like endoplasmic reticulum kinase)." (PMID 38539069, 2024).
Peri-Implantitis (1 paper, 2019). An inflammatory process with loss of supporting bone in the tissues surrounding functioning DENTAL IMPLANTS. "Three leader genes (PSMD10, SOS1, WASF3), eight cross-talk genes (PSMD10, PSMD6, EIF2S1, GSTP1, DNAJC3, SEC61A1, MAPT, and NME1), and one signaling pathway (IL-17 signaling) emerged as peri-implantitis and T2DM linkage mechanisms." (PMID 31275749, 2019).
retinal degeneration (1 paper, 2025). Degeneration of the retina. "Depletion of seven genes (Eif2s1, Hspa5, Hspa8, Nploc4, Hyou1, Ufd1, and Vcp) showed an exacerbating effect on the Rho-Pro23His retinal degeneration compared to the Cas9+/− mice." (PMID 41282224, 2025).
squamous cell carcinoma (1 paper, 2025). A carcinoma arising from squamous epithelial cells. "In contrast, in squamous cell carcinoma, inhibition of EIF2S1 is compensated for by an alternative translation initiation factor, EIF2A, thereby sustaining the survival of squamous cell carcinoma despite the inhibition of EIF2S1." (PMID 40365898, 2025).
cancer (20 papers, 2011 to 2025). A tumor composed of atypical neoplastic, often pleomorphic cells that invade other tissues. "In several cancer types, increased expression levels of EIF2S1 are associated with more aggressive types of cancer." (PMID 40365898, 2025). "However, given that EIF2S1 promotes the survival and progression of certain cancer cells and is associated with poor prognosis in BCa, targeting EIF2S1 may be a potential therapeutic option in BCa management." (PMID 40365898, 2025). "We further corroborated the prognostic significance of the EIF2S1 gene using a Kaplan–Meier (KM) plotter-based survival analysis of The Cancer Genome Atlas (TCGA)-NB database." (PMID 39465005, 2024). "We observed elevated EIF2S1 expression in human papillomavirus (HPV)-positive cancers compared to the normal epithelium and even higher expression levels in HPV-negative samples." (PMID 38001610, 2023). "Multivariate Cox regression showed that seven cancer-essential FRGs (ISCU, NFS1, MTOR, EIF2S1, HSPA5, AURKA, and RPL8) were significantly associated (p<0.05) with OS." (PMID 35756689, 2022). "After multivariate and LASSO analyses, seven cancer-essential FRGs (ISCU, NFS1, MTOR, EIF2S1, HSPA5, AURKA, and RPL8) were used to construct the risk model." (PMID 35756689, 2022). "Twenty genes were found mutated orwith copy number alterations in at least five percent of three cancer cohortsand six of them (PHOX2A, NFYC, EST2, EIF2S1, SSRP1 and PARP1) associated withimpacted patient survival." (PMID 32159609, 2020). "They include APOA1, VEGFC, YWHAZ, B2M, EIF2S1, CCR9 and many other genes that have been associated with the hallmarks of cancer." (PMID 25986937, 2015). "eIF2α (EIF2S1) is a master regulator of translation dysregulation in cancer." (PMID 38954770, 2024). "Hence, the dysregulation of eIFs and eEFs has been demonstrated in many human cancers, e.g., EIF2S1 was shown to resist cell death during paclitaxel treatment of cells." (PMID 34830804, 2021). "EIF2S1 promoted tumorigenesis by activating autophagy and enhancing tumor formation, enabling tumor cells to survive in a hypoxic and a low glucose microenvironment, making it an attractive target in Myc-driven cancer." (PMID 33771191, 2021). "Therefore, there is a possibility of adverse effects when RPS3, EIF2S1 and/or RBM8A are targeted in cancer therapy." (PMID 34202873, 2021). "EIF2S1 is elevated in both HPV-positive and negative HNSCC, yet the expression is higher in HPV- (n = 434) than in HPV+ cancers (n = 80; p = 1.36 × 10−3)." (PMID 38001610, 2023). "Our functional assay showed that growth suppression was induced in non-cancerous cells by the downregulation of three RBPs (RPS3, EIF2S1, RBM8A), suggesting that these molecules have pivotal functions in proliferation and apoptosis in non-cancerous cells as well as cancer cells." (PMID 34202873, 2021).
tumor (18 papers, 2007 to 2025). "Chi-square test results comparing clinicopathological demographics between high and low-EIF2S1-expressing NB patients showed that upregulation of EIF2S1 was positively associated with tumor stage, risk of NB, and incidence of distant metastasis." (PMID 39465005, 2024). "Our functional experiments in vitro and in vivo further showed that silencing EIF2S1 leads to reduced NB cell proliferation, impaired migration and invasion, and retarded tumor growth in animal models." (PMID 39465005, 2024). "Immunohistochemical staining in the tumor tissues showed a significant decrease of Ki67-positive cells in the samples with EIF2S1 silencing, further indicating the impeded cell proliferation in vivo (p < 0.05)." (PMID 39465005, 2024). "To further evaluate the impact of EIF2S1 on NB tumorigenesis in vivo, we generated xenograft tumor models using SK-N-SH cells expressing sh-EIF2S1 or sh-NC, since SK-N-SH cells exhibited the highest level of EIF2S1 among all NB cell lines." (PMID 39465005, 2024). "NB tissues exhibited significantly higher EIF2S1 mRNA levels compared to tumor-free tissues from healthy counterparts (p < 0.001)." (PMID 39465005, 2024). "Taking into account all investigated eIFs, eIF6 appears to play the most important role in ITACs, followed by eIF2S1, with increased expression in tumour tissues compared with normal controls." (PMID 34830804, 2021). "For example, Celf1 promotes expression of Cebpb via interacting with Eif2s1 and Eif2s2 in proliferating livers and in tumor cells." (PMID 32546682, 2020). "It is interesting to note that reduced expression of keratin 15 (KRT15) is associated with increased expression of the translation factor EIF2S1 in the prediction model for increased elastase, which in turn predicts a lower stage tumor." (PMID 19455237, 2007). "Importantly, our in vitro and in vivo experiments demonstrated that EIF2S1 silencing attenuated the aggressiveness of NB cells and resulted in a reduction in tumor burden in nude mice, providing important evidence supporting an oncogenic role of EIF2S1 in NB." (PMID 39465005, 2024). "By suppressing EIF2S1 expression or activity, we may be able to induce ferroptosis in NB cells, thereby inhibiting tumor growth and metastasis." (PMID 39465005, 2024). "Moreover, our findings on immune infiltration in NB highlight the need for further investigation into the complex interplay between EIF2S1 expression, immune cell populations, and tumor microenvironment." (PMID 39465005, 2024). "EIF2S1, EIF2S2, and EIF2S3 were all reported to associate tumor progression." (PMID 31258820, 2019). "EIF2S1 controls GPX4 and SLC7A11 expression to protect tumor cells from ferroptosis, thus promoting tumor growth." (PMID 40302793, 2025). "Three genes from the PERK pathway (EIF2S1, EIF2AK3, and DDIT3) showed a positive correlation with the SCNA score across almost every tumor type." (PMID 34698427, 2021). "Immunohistochemical staining showed that the tumours treated with doxycycline exhibited lower expression of EIF2A and stronger phosphorylated EIF2S1 than that in the controls." (PMID 31211507, 2019). "Here we performed in silico analyses, evaluated the protein levels of EIF2S1, EIF5A and EIF6 in tumour samples and non-neoplastic tissue controls obtained from 145 patients, and correlated these results with clinical outcome data, including tumour site, stage, adjuvant radiotherapy and survival." (PMID 34830804, 2021).
neurodegenerative disease (4 papers, 2018 to 2026). A disorder of the central nervous system characterized by gradual and progressive loss of neural tissue and neurologic function. "EIF2S1, eukaryotic translation initiation factor 2 subunit-α, is a translation initiation factor, and phosphorylation of EIF2S1 is involved in neurodegenerative diseases." (PMID 36819777, 2023).
urological diseases (1 paper, 2025). "Further investigation is needed to evaluate whether concomitant urological diseases could influence the amount of EIF2S1 in uEVs." (PMID 40365898, 2025).
EIF2S1 also shares sentences with these, for which no sentence is quoted: infection (7 papers); viral infection (5); Alzheimer disease (2); colon cancer (2); fatty liver disease (2); memory impairment (2); Obesity (2); Bladder Cancer (1); breast tumours (1); cognitive deficits (1); dementia (1); Dengue virus infection (1); esophageal cancer (1); glioma (1); Hematuria (1); Herpes simplex infection (1); HIV-1 infection (1); intestinal type adenocarcinoma (1); iron deficiency (1); liver steatosis (1); mastitis (1); multiple myeloma (1); multiple sclerosis (1); neuroblastoma (1); neuropathy (1); non-small cell lung carcinoma (1); pancreatic cancer (1); prion disease (1); renal cell carcinoma (1); schizophrenia (1).
A further 3 diseases each share a sentence with EIF2S1 in 1 paper.